DUSP8 (dual specificity phosphatase 8)
Diseases named in the same sentence as DUSP8 in open-access papers (continued):
Sharing a sentence is not in itself a finding about the gene and the disease.
asthma (1 paper, 2023). "DUSP8 production and DUSP8–Pur-α interaction are induced in the cytoplasm of Th9 cells from people with asthma and patients with atopic dermatitis." (PMID 37909329, 2023). "Remarkably, DUSP8 protein levels and the DUSP8–Pur-α interaction were indeed increased in the cytoplasm of T cells from people with asthma and patients with atopic dermatitis." (PMID 37909329, 2023). "Consistently, among 25 phosphatases of the DUSP phosphatase family, only DUSP8 proteins in T cells of people with asthma were induced, detected by mass spectrometry-based proteomics." (PMID 37909329, 2023). "The induction of DUSP8 and IL-9 in the same T cells of people with asthma were also detected by immunofluorescence staining." (PMID 37909329, 2023). "As expected, DUSP8 proteins were colocalized with Pur-α in the cytoplasm of T cells from people with asthma." (PMID 37909329, 2023). "Remarkably, DUSP8 was detected in 5 of 6 patients with asthma, whereas DUSP8 was detected in only 1 of 6 people in the control group." (PMID 37909329, 2023). "The concomitant induction of DUSP8 and IL-9 in peripheral blood T cells of people with asthma and AD supports that DUSP8 induces IL-9 production." (PMID 37909329, 2023). "Our data showed that the induction of asthma phenotypes in the mouse model was attenuated by T-cell-specific DUSP8 cKO." (PMID 37909329, 2023). "Moreover, the nuclear export of Pur-α and the cytoplasmic interaction between DUSP8 and Pur-α also occurred in the peripheral blood T cells of people with asthma and atopic dermatitis." (PMID 37909329, 2023). "DUSP8 may be a T-cell biomarker and therapeutic target for asthma and atopic dermatitis." (PMID 37909329, 2023).
atopic dermatitis (1 paper, 2023). "Furthermore, DUSP8 induction in T cells also occurred in T cells of people with atopic dermatitis." (PMID 37909329, 2023).
cardiomyopathy (1 paper, 2022). A disease of the heart muscle or myocardium proper. "Depletions of different DUSPs in mice have shown changes in cardiomyocyte morphology (DUSP8,), or have been linked to protection (DUSP6,) or, in contrast, to increased susceptibility to cardiomyopathy (DUSP1, DUSP4,)." (PMID 36227898, 2022).
Cerebral ischemia (1 paper, 2019). Restriction of arterial blood supply to the brain associated with insufficient oxygenation to support the metabolic requirements of the tissue. "The inhibitor of DUSP8, anisomycin, might elevate JNK activity following postischemic reperfusion, indicating that DUSP8 was closely correlated with inactivation of JNK following cerebral ischemia." (PMID 31467668, 2019).
cervical squamous cell carcinoma (1 paper, 2024). A squamous cell carcinoma arising from the cervical epithelium. "Moreover, DUSP8 is not exclusively downregulated in LUAD, but it is also downregulated in pancreatic ductal adenocarcinoma (PDAC), kidney renal papillary cell carcinoma (RPCC), and cervical squamous cell carcinomas (CSCC), again being associated with poor OS." (PMID 38396293, 2024).
glial tumors (1 paper, 2025). "Interestingly, among the transcripts down-regulated in DUSP8-GFP GdEC#1 and up-regulated in sh-DUSP8-GFP GdEC#1 we found periostin (POSTN) a matricellular protein that has been associated with glioma progression, particularly with glioma angiogenesis." (PMID 41029387, 2025). "Among the transcripts down-regulated in DUSP8-GFP GSC#1 and up-regulated in sh-DUSP8-GFP GSC#1 we found stanniocalcin-1 (STC1), a secreted glycoprotein associated with poor prognosis, glioma grade, and resistance to TMZ therapy." (PMID 41029387, 2025). "Specifically, glial tumor cells with high expression of DUSP8 (cytoplasmic expression) showed low expression of miR-1825 (cytoplasmic and nuclear expression), while glial cells with low DUSP8 expression showed higher expression of miR-1825." (PMID 41029387, 2025). "Interestingly, among the transcripts down-regulated in DUSP8-GFP GdEC#1 and up-regulated in sh-DUSP8-GFP GdEC#1 we found POSTN, a matricellular protein that has been associated with glioma progression, particularly with glioma angiogenesis." (PMID 41029387, 2025).
leukemia (1 paper, 2019). A malignant (clonal) hematologic disorder, involving hematopoietic stem cells and characterized by the presence of primitive or atypical myeloid or lymphoid cells in the bone marrow and the blood. "In K562 human leukemia cells, PMA treatment promptly induced DUSP8 transcripts, and activated the expression of M3/6 (murine DUSP8) completely suppressed PMA-induced phosphorylation of JNK/SAPK." (PMID 31467668, 2019).
liver fibrosis (1 paper, 2022). "Among all these analyzed DUSPs, DUSP3, DUSP8, DUSP12, DUSP14, DUSP16, DUSP22, and DUSP26 were significantly decreased in the liver of NASH patients with obvious hepatocyte ballooning, severe inflammatory infiltrate, and pattern of liver fibrosis compared with the normal individuals." (PMID 36209205, 2022).
lung adenocarcinoma (1 paper, 2024). A carcinoma that arises from the lung and is characterized by the presence of malignant glandular epithelial cells. "In this study, we found that DUSP8 is silenced by miR-147b in patients with lung adenocarcinoma (LUAD), which correlates with poor overall survival." (PMID 38396293, 2024).
multiple myeloma (1 paper, 2022). "Moreover, we found that YY1 mutation could affect the expression changes of certain genes in some cancers; for example, in multiple myeloma, YY1 mutation could affect the expressions of ERMN, DUSP8, PRG2, BMF, and RNASE2 genes." (PMID 35791393, 2022).
SARS-CoV infection (1 paper, 2013). "Similarly, DUSP8, IL6, CXCL10, and NFKBIA are up-regulated in SARS patients, while PTX3 and CXCL2 have been shown to be involved in SARS-CoV infection." (PMID 23935999, 2013).
Sepsis (1 paper, 2020). Sepsis is defined as life-threatening organ dysfunction caused by a dysregulated host response to infection. "At a log2FC>2 (adjusted P < 0.05) MAPK related genes F2rl1, Adm (marked as multi, as it was picked up for term searches “metabolic,” “hypoxia,” and “MAPK”), Mapk4, Gdf15, Dusp10, and Dusp8 were up-regulated in Isoflurane-Sepsis compared to only 2 genes in the Propofol-Sepsis group." (PMID 33392215, 2020).
viral infection (1 paper, 2024). "MAPK/ERK hyperactivity is brought on by viral infection, specifically EBV infection, that could be mediated by DUSP-8 and DUSP-6 (MKP-3) downregulation." (PMID 39144488, 2024).
cancer (10 papers, 2013 to 2025). A tumor composed of atypical neoplastic, often pleomorphic cells that invade other tissues. "So far, however, the role of DUSP8 in cancer and the molecules involved in the post-transcriptional regulation of DUSP8 remain barely investigated." (PMID 38396293, 2024). "This is the first time we demonstrated that the DUSP8 mediated pathway plays a pivotal anti-cancer role on ASOs against miR-21 inhibiting the growth and metastasis of CRC." (PMID 31467668, 2019). "Among these upregulated genes, Dennd4a, Nfil3, Hspa1b, Chac1, Ddit4, Mex3b, Lysmd3, and Zbtb10 are mainly involved in oxidative stress and inflammation response, whereas Plcxd2, Dusp1, Cep85l, and Dusp8 are generally considered as tumor‐suppressor genes by inhibiting proliferation of cancer cells." (PMID 40231790, 2025). "DUSP8 is emerging as a critical negative regulator MAPKs pathway and is involved in cell oxidative stress response and apoptosis, as well as, in several diseases, including cancer." (PMID 41029387, 2025). "Moreover, DUSP8 restoration increased sensitivity of GdEC#1 to ralimetinib treatment whereas GdEC#1 sh-DUSP8-GFP showed a decreased sensitivity confirming the critical role of DUSP8 in determining sensitivity to cancer therapeutics." (PMID 41029387, 2025). "Until now, the role of DUSP8 in the progression of cancer has been largely neglected." (PMID 38396293, 2024). "To more closely examine the contribution of DUSP8 to tumor suppression, we used a xenograft model, finding significantly reduced cancer cell proliferation and tumor size as well as vessel formation and EMT marker change upon DUSP8 overexpression." (PMID 38396293, 2024). "Via its interaction with DUSP8 and thereby major MAPK signaling cascades, miR-147b promotes tumor cell proliferation and migration, inhibits cancer cell apoptosis and enhances EMT signatures, thus offering a novel target for therapeutic intervention." (PMID 38396293, 2024). "DUSP8 is a phosphatase that dephosphorylates and deactivates JNK and p38 MAPKs, and it was shown to inhibit cell proliferation and migration of cancer cells." (PMID 37834191, 2023). "DUSP8 is emerging as a critical negative regulator for Mitogen-activated protein kinase (MAPK) pathway and it is involved in cell oxidative stress response and cell apoptosis, as well as the development of various human diseases, including cancer." (PMID 41029387, 2025). "The functional assays depicted a suppression of cancer cell proliferation, colony formation, migration, no change in apoptosis and corresponding EMT markers (CK18 and VIM), predicated on DUSP8 upregulation." (PMID 38396293, 2024). "In addition, other cancer types (e.g., PDAC, RPCC, and CSCC) showed the same correlation between DUSP8 expression and survival as LUAD." (PMID 38396293, 2024). "The role of DUSP2 and DUSP8 genes coding phosphatases regulating MAPK signaling pathway confirmed the contribution of these target genes to the development and progression of many cancers." (PMID 27152840, 2016). "However, DUSP8 and DUSP16 did not seem to play a major role in the regulation of basal JNK phosphorylation levels in other cancer cell lines, suggesting that different ROS-regulatable phosphatases might control the basal JNK activity in different types of tumour cells." (PMID 24115572, 2013).
tumor (9 papers, 2013 to 2025). "The reduction of tumor volume was confirmed by Ki67 labeling identifying a decreased number of proliferating cells in DUSP8-GFP tumors further reduced in sh-DUSP8-GFP, as compared with GFP GSC#1 cells." (PMID 41029387, 2025). "In the early stages of tumor development, DUSP8 is in the “on” state, promoting proliferation while maintaining the undifferentiated characteristics of stem-like cells." (PMID 41029387, 2025). "Surprisingly, both stable enforced expression and silencing of DUSP8 in GSC#1 dramatically reduced tumor growth following intracerebral injection into the striatum of NOD-SCID mice." (PMID 41029387, 2025). "To determine the tumor-suppressive properties of DUSP8 overexpressing cells in vivo, we transplanted A549-DUSP8 OE and A549-EV cells subcutaneously into the right flank of NOD.Cg-Prkdcscid Il2rgtm1Wjl/SzJ (NSG) immunodeficient mice." (PMID 38396293, 2024). "Overexpression of DUSP8 resulted in a tumor-suppressive phenotype in vitro and in vivo experimental models, whereas silencing DUSP8 with a siRNA approach abrogated the tumor-suppressive properties." (PMID 38396293, 2024). "Knockdown of miR-147b restored DUSP8, decreased tumor progression in vitro, and increased apoptosis via JNK phosphorylation." (PMID 38396293, 2024). "On the contrary, when the tumor nodule has reached a certain limit size and requires oxygen and nutrients, the DUSP8 switch goes into “off” mode and the tumor cells begin to contribute to the formation of blood vessels and to migrate, infiltrating the surrounding tissue." (PMID 41029387, 2025). "In the present study we identified a three miRNA signature that clearly distinguish GSCs cultivated in stem cell medium or differentiated in endothelial conditions and are able to regulate GSC-contribution to tumor vascularization through dual-specificity phosphatase 8 (DUSP8) modulation." (PMID 41029387, 2025). "In addition, we were able to rescue the tumor suppressive phenotype in A549-miR-147b OE cells via overexpression of DUSP8, confirming the impact of miR-147b mediated inhibition." (PMID 38396293, 2024). "Furthermore, DUSP8 overexpressing tumors revealed a significantly increased number of apoptotic cells in the tumor area and decreased numbers of proliferating cells and blood vessels in the tissue samples compared to the EV-inoculated control group." (PMID 38396293, 2024). "However, genes involved in antioxidant defense (GSTO1), apoptosis process (DUSP8), and tumor suppressor (KIAA1324, FBXO47, NME6) were upregulated in mycotoxins-exposed animals, suggesting activation of the antioxidant defense in response to mycotoxicity." (PMID 37744913, 2023). "Notably, we could detect increased DUSP8 expression at the mRNA and protein levels in the tumor tissue after 40 days of tumor growth." (PMID 38396293, 2024). "Sodium selenite treatment upregulated pro-apoptotic, apoptotic, and tumor suppressor genes such as ATF3, FOSB, GADD45B, DUSP8 and ACHE, and downregulated tumor cell survival genes such as SCD, LRP1, RAB31, SRPX2, PDK1 and CSGALNACT1." (PMID 36059619, 2022). "In this sense, we evaluated the prognostic value of the ZNF611, ZNF304, RIPK1, TNFRSF21, DUSP8 and HRAS genes according to tumor subtypes." (PMID 30938061, 2019). "On the other hand, the variable effects of JNK and p38 MAPKs on NB cell apoptosis endorse the possibility of a beneficial use of inhibitors of JNK- or p38-specific MKPs, such as DUSP1, DUSP8, DUSP10, or DUSP16, but only in NB cases in which the activity of JNKs or p38s favors tumor chemosensitivity." (PMID 30866462, 2019). "At 16 weeks after grafting the volume of the brain invaded by tumor cells was 39.9 ± 1.2 mm3, 15.1 ± 0.6 mm3 and 10.5 ± 0.7 mm3 in mice grafted with GFP, DUSP8 GFP and sh-DUSP8 GFP GSC#1, respectively (mean ± SD, p = 0.001, DUSP8-GFP vs GFP; p = 0.001, sh-DUSP8-GFP vs GFP, Student-t test)." (PMID 41029387, 2025).
tumor (continued). "The volume of the brain invaded by tumor cells at 12 weeks after grafting was 26.9 ± 0.8 mm3, 4.9 ± 1.2 mm3 and 1.8 ± 0.1 mm3 in mice grafted with GFP, DUSP8-GFP and sh-DUSP8-GFP GSC#1, respectively (mean ± SD, p = 0.002, DUSP8-GFP vs GFP; p = 0.0005, sh-DUSP8-GFP vs GFP, Student-t test)." (PMID 41029387, 2025).
infection (2 papers, 2024). The state of being infected such as from the introduction of a foreign agent such as serum, vaccine, antigenic substance or organism. "Key markers such as ZBTB10, DUSP8, and HIST1H2BG, predominantly expressed in VRI_stage2, suggest specialized roles during infection beyond the transitional differentiation observed in uninfected conditions." (PMID 39735182, 2024).
DUSP8 also shares sentences with these, for which no sentence is quoted: glioblastoma (2 papers); psoriasis (2); allergic asthma (1); Allergy (1); bladder cancer (1); brain tumors (1); cardiac hypertrophy (1); COVID-19 (1); glioma (1); Glucose intolerance (1); hepatocellular carcinoma (1); meningioma (1); Myocardial fibrosis (1); myopathy (1); pancreatic ductal adenocarcinoma (1); prostate carcinoma (1); systemic lupus erythematosus (1); type 1 diabetes mellitus (1); ulcerative colitis (1); uterine cancer (1); Vestibular schwannoma (1).